MLH3 (mutL homolog 3)
Description:
Probably involved in the repair of mismatches in DNA.
Synonyms: HNPCC7
Tractability: PROTAC: ubiquitination databases record sites on it.
Gene: Protein-coding gene on chromosome 14 (75,013,769 to 75,051,532, reverse strand). Ensembl gene ENSG00000119684.
Subcellular location: Nucleus
Subcellular location (Human Protein Atlas): Nucleoplasm
Pathways (Reactome):
Reproduction: Meiotic recombination
Gene Ontology:
Molecular function: protein binding; ATP hydrolysis activity; satellite DNA binding; ATP binding; ATP-dependent DNA damage sensor activity; mismatched DNA binding
Biological process: mismatch repair; reciprocal meiotic recombination
Cellular component: MutLgamma complex; mismatch repair complex; nucleus
Genetic constraint (gnomAD): Loss-of-function variants: 72 observed, 119.18 expected, observed/expected ratio (o/e) 0.6, 90% interval 0.5 to 0.74. The upper end of that interval is the gene's LOEUF score, 0.74, which puts it in group 3 of 6, group 1 being the genes least tolerant of losing a copy. Missense variants: 1,466 observed, 1,726 expected, observed/expected ratio (o/e) 0.85, 90% interval 0.81 to 0.89. Synonymous variants: 512 observed, 611.27 expected, observed/expected ratio (o/e) 0.84, 90% interval 0.78 to 0.9.
Gene-disease validity (ClinGen):
ClinGen rates the evidence that MLH3 causes each of these diseases.
colorectal cancer, hereditary nonpolyposis, type 7 (autosomal dominant): Limited.
intestinal polyposis syndrome (autosomal recessive): Limited. A syndrome associated with the development of multiple polyps throughout the intestine.
Homologues: Orthologues: chimpanzee MLH3 (99% identical), macaque MLH3 (95% identical), pig MLH3 (81% identical), guinea pig MLH3 (79% identical), rabbit MLH3 (77% identical), dog MLH3 (77% identical), mouse Mlh3 (72% identical), rat Mlh3 (72% identical), tropical clawed frog mlh3 (40% identical), zebrafish mlh3 (32% identical). Paralogues in human: PMS1 (12% identical), MLH1 (12% identical), PMS2 (11% identical).
Diseases named in the same sentence as MLH3 in open-access papers:
MLH3 is named in the same sentence as 59 diseases in open-access papers, as found by Europe PMC text mining. Sharing a sentence is not in itself a finding about the gene and the disease. The quoted sentences say what the papers report.
Lynch syndrome (17 papers, 2006 to 2024). An autosomal dominant hereditary neoplastic syndrome characterized by the development of colorectal carcinoma and a high risk of developing endometrial carcinoma, gastric carcinoma, ovarian carcinoma, renal pelvis carcinoma, and small intestinal carcinoma. "Variants have also been found together with other MMR gene variants, suggesting PMS1 and MLH3 to be low risk genes in Lynch syndrome." (PMID 27696107, 2017). "One of the variants was previously reported to cause Lynch syndrome (MLH3) and the other to cause Renal cell carcinoma/MODY type 3 (HNF1A)." (PMID 24884844, 2014). "It has been proposed that one additional mismatch repair gene, mutL homolog 3 (MLH3), also plays a role in Lynch syndrome predisposition, but the clinical significance of mutations in this gene is less clear." (PMID 19466295, 2009). "The region comprises the MLH3 gene that is linked to hereditary non-polyposis colorectal cancer type 7 (HNPCC7)." (PMID 16982006, 2006). "Both MLH3 and PMS1 genes are suspected to play a role in Lynch syndrome, but the clinical significance of variants in these genes is less clear." (PMID 37656691, 2023). "Patient 75 is a carrier of VUS (c.1755dupA, p.Glu586fs, and rs751465048) in the MLH3 gene, which is part of the MMR machinery associated with Lynch syndrome." (PMID 32695137, 2020). "Germline mutations in MLH3 have been associated with the Lynch syndrome, although not fulfilling the Amsterdam I criteria, and with an unclear clinical role." (PMID 29368212, 2018). "MLH3 gene may also be mutated in the germline in some suspected Lynch syndrome families with a variable degree of MSI in tumor tissue, but there is little evidence to support its role in predisposition to classical Lynch syndrome." (PMID 19516960, 2008). "MLH3 gene encodes a protein that functions as a heterodimer with other MMR genes, and PMS1 gene encodes a protein that forms a heterodimer with MLH1 and PMS2, products of MMR genes involved in Lynch syndrome (nonpolyposis colorectal cancer, HNPCC)." (PMID 37656691, 2023). "This redundancy also may help to explain the low prevalence and penetrance of PMS2 mutations in MMR-deficient colon cancers and the reported lack of biochemical data to support MLH3 in Lynch syndrome." (PMID 23450065, 2013).
colorectal cancer (15 papers, 2005 to 2025). A primary or metastatic malignant neoplasm that affects the colon or rectum. "But in the screening of colorectal cancer patients, tumors harboring MLH3 mutations were identified as microsatellite-stable, suggesting that MLH3 does not promote carcinogenesis through classical DNA mismatch repair deficiency but may act via alternative pathways." (PMID 40356752, 2025). "Those genes play an important role in the repair processes after DNA damage and mlh3 has been reported in the endometrial carcinoma and colorectal cancer." (PMID 32541658, 2020). "Since PMS1, MLH3 and EXO1 have only been implicated in the development of colorectal cancers in case reports, they are unlikely to be implicated in the development of cancer in our group." (PMID 16106253, 2005). "The genes MSH3 and MLH3 are known cancer genes originally identified in colorectal cancer." (PMID 39272813, 2024). "Researchers found no clear relationship between mutations in the MLH3 gene and the development of colorectal cancer." (PMID 38201513, 2023). "Several studies have been conducted on the possible relationship between the presence of germline mutations in MLH3 and the development of hereditary nonpolyposis colorectal cancer." (PMID 38201513, 2023). "In addition, the genotypes CC and TC in MLH3 rs108621 compared with TT allele and ERCC1 rs3212986 AA variant have predominantly enhanced the risk of colorectal cancer in males." (PMID 35330456, 2022). "The binding of miRNA-193a-3p to MLH3 rs108621 site was identified as a predictor factor of C.R.C. Hence, miR-193a-3p could act as a biomarker to predict colorectal cancer." (PMID 35330456, 2022). "Additionally, when DSBs are induced by gamma-radiation, Mlh1, Pms2 and Mlh3 mutant MEFs have higher DR copy number alterations (CNAs), including DR CNA hotspots previously identified in mouse MMR-deficient colorectal cancer (dMMR CRC)." (PMID 29069730, 2017). "The role of MLH3 in colorectal cancer remains controversial." (PMID 24759751, 2014).
breast carcinoma (13 papers, 2009 to 2026). "Recently, germline variants in MLH3 gene have been reported in Finnish families with adenomatous polyposis who also exhibited breast cancer, and in Chinese patients with breast/ovarian cancer." (PMID 37656691, 2023). "It has been reported that a single nucleotide polymorphism (SNP)–SNP interaction between MSH4 Ala97Thr/MLH3 Leu844Pro increases breast cancer susceptibility." (PMID 36076047, 2022). "MLH3 polymorphisms were shown to be associated with the risk of lung cancer and breast cancer, and MLH3 mutation has a role in endometrial cancers." (PMID 24759751, 2014). "We also found evidence for an interaction (MSH4 Ala97Thr/MLH3 Leu844Pro) associated with an increased risk for breast cancer." (PMID 19781088, 2009). "In summary, we found that the genetic variant of the MLH3 gene, Leu844Pro, was associated with decreased risk for breast cancer." (PMID 19781088, 2009). "The first plausible association was for MLH3 (Leu844Pro) a non-synonymous variant being related with a reduced risk for the homozygous (Pro/Pro) and the heterozygous (Leu/Pro) individuals on breast cancer susceptibility." (PMID 19781088, 2009). "Further, reduced MLH3 expression was observed in individuals diagnosed with grade II and III breast cancer, suggesting MLH3 may serve as a reliable susceptibility marker." (PMID 38577257, 2023). "Also, families with more recently described polyposis predisposition syndrome caused by biallelic mutations in MLH3 gene were reported to have extracolonic tumors, including breast cancer." (PMID 32949222, 2020). "The GA and AA genotypes of MLH3 rs175080 were associated with a low risk of breast cancer." (PMID 29516665, 2018). "MLH3 polymorphisms are reported to be related to the risk of lung and breast cancer." (PMID 24759751, 2014). "Moreover, combined mutations in MSH4 and MLH3 were associated with increased risk of breast cancer." (PMID 36076047, 2022). "In a previous study in Saudi Arabian breast cancer patients, 37 potential variants in 25 breast cancer risk associated genes other than BRCA1/2 were identified including variants in MLH1, MLH3 genes." (PMID 37656691, 2023). "Mainly, exploration of the impact of MLH3 and PMS1 germline variants in breast cancer would require further segregation analysis and screening tests such as MSI test in larger breast cancer cohorts." (PMID 37656691, 2023). "We carried out a hospital-based case-control study in a Caucasian Portuguese population (287 cases and 547 controls) to estimate the susceptibility to non-familial breast cancer associated with some polymorphisms in mismatch repair genes (MSH3, MSH4, MSH6, MLH1, MLH3, PMS1 and MUTYH)." (PMID 19781088, 2009). "However, low-risk genes such as MLH3 and PMS1 are not available in the management guidelines, where variants in low-penetrance genes are very rare and correlate with < 2-fold risk of developing breast cancer." (PMID 37656691, 2023).
lung carcinoma (7 papers, 2009 to 2021). "Among DDR genes identified, MLH3 mutation was found associated with worse OS compared with wild-type in whole lung cancer patients." (PMID 34604048, 2021). "In this study, seven candidate SNPs in 3′UTR of DRC‐related genes including ERCC1 (rs3212986, rs2336219, and rs735482), OGG1 (rs1052133), MLH3 (rs108621), CD3EAP (rs1007616), and PPP1R13L (rs6966) were analyzed in 300 lung cancer patients and controls from the northeast of China." (PMID 30453383, 2018).
polyposis (6 papers, 2017 to 2026). "The presence of biallelic variants is implicated in polyposis syndromes with an AFAP-like phenotype (adenomatous polyposis at early age and extracolonic malignant and benign lesions) called MSH3/MLH3-associated polyposis." (PMID 37239385, 2023). "MLH3 (MutL Homolog 3) is the altered gene in MLH3-associated polyposis, and the encoded protein MLH3 plays a role in maintaining genomic integrity during DNA replication and after meiotic recombination." (PMID 37239385, 2023). "Multiple colonic adenomas are characteristic of PPAP (0–100 cumulative polyps), NTHL1 tumor syndrome (1–100 cumulative polyps), MLH3-associated polyposis (10–100 cumulative polyps), and LF (colorectal polyps)." (PMID 37239385, 2023). "The truncating MLH3 mutation c.3563 C > G, p.Ser1188* was found in homozygote state in an unexplained polyposis case (IV:69) with duodenal polyps and CRC." (PMID 27696107, 2017). "Other MMR genes may contribute to cancer susceptibility with lower penetrance (MLH3) or predispose to polyposis (MSH3, MLH3)." (PMID 32660107, 2020).
endometrial carcinoma (5 papers, 2014 to 2025). A malignant tumor arising from the epithelium that lines the cavity of the uterine body. "In the available cohort study of MLH3 mutations, a family index case was found to have endometrial cancer along with her daughter and thought 80-year-old aunt." (PMID 40356752, 2025). "This is why we believe that MLH3 plays a crucial role in the development of endometrial cancer in this low-risk family." (PMID 40356752, 2025). "This study presents two cases of endometrial cancer to investigate the impact of germline mutations in MLH3 on carcinogenesis and its mechanisms, potentially broadening the scope of genetic testing for endometrial cancer." (PMID 40356752, 2025). "In this case report, we reported that two related mothers and daughters had mutations in some of their germline genes, with MLH3 as a possible low-risk gene for endometrial cancer, which we further explored as contributing to the development of endometrial cancer." (PMID 40356752, 2025). "Similar to the mother and daughter in this case, as a microsatellite-stable MLH3 mutant cancer population, germline mutations lead to increased tumor susceptibility in patients, and the existence of synergistic effects with other mutations causing endometrial cancer cannot be excluded." (PMID 40356752, 2025). "They concluded that MLH3 participated in the endometrial carcinoma pathogenicity by changing the function of protein MLH3 instead of altering its expression." (PMID 24759751, 2014). "Building upon these findings, we utilized two representative endometrial carcinoma cases to investigate the role of MLH3 in the pathogenesis and progression of endometrial cancer, with the aim of further elucidating its molecular mechanisms in oncogenic processes." (PMID 40356752, 2025). "In this case, the patient’s genetic test results showed microsatellite stability without MLH3 somatic mutation, but it still does not exclude MLH3 as a possible causative factor for the development of endometrial carcinoma, as in atypical HNPCC." (PMID 40356752, 2025).
Huntington disease (5 papers, 2013 to 2024). Huntington disease (HD) is a rare neurodegenerative disorder of the central nervous system characterized by unwanted choreatic movements, behavioral and psychiatric disturbances and dementia. "Despite its clear role in repeat expansion, no modifier haplotypes are reported to associate with MLH3 in the Genetic Modifiers of Huntington's Disease (GeM-HD) Consortium GWASs." (PMID 38749429, 2024). "Another event was recovered in MLH3, which plays a role in the DNA mismatch repair pathway (MMR) and is connected to Huntington’s disease and the somatic expansion of CAG repeats." (PMID 37111604, 2023).
Infertility (5 papers, 2013 to 2025). "MLH3 is required for cross-over-specific resolution of recombination precursors and loss of MLH3 leads to infertility in mice." (PMID 41292753, 2025). "In this study the functional polymorphisms of MLH3 C2531T was investigated in Iranian women with unexplained infertility." (PMID 24639688, 2013). "The genotype frequency of MLH3 C2531T polymorphisms in our study subjects were significantly different between the patients with unexplained infertility and normal controls (p=0.0001)." (PMID 24639688, 2013). "It is likely that various polymorphisms of the MLH3 gene may result in male infertility, based on findings related to the presence of the MLH3 C2531T polymorphism in infertile men." (PMID 28157160, 2017). "Interestingly, men with missense mutation (C2531T) in MLH3 gene have an increased risk of infertility." (PMID 24639688, 2013). "Therefore, our data suggest that the MLH3 C2531T polymorphism can be associated with the risk of unexplained infertility in Iranian women." (PMID 24639688, 2013). "In the present study, there was a statistically significant difference between the groups of infertile women compared to the control group (p=0.0001) with regard to the MLH3 C2531T polymorphism, suggesting that this polymorphism might be related to women infertility." (PMID 24639688, 2013). "Therefore, the MLH3 gene polymorphism may be a genetic risk factor for unexplained infertility in women." (PMID 24639688, 2013). "Similar to the situation seen for Mlh3-/- males, Mlh3DN/DN males show complete infertility, accompanied by significantly reduced testes size when compared to WT (p < 0.0001) and the absence of spermatozoa in the epididymides (p < 0.0001)." (PMID 31170160, 2019). "Although there are no studies about mutations of the MLH3 gene in the female infertile cases, these mutations are likely to be causative for female infertility, because infertility phenotype is observed previously in female mice with an Mlh3 deficiency." (PMID 24639688, 2013). "Both male and female Mlh1-/- and Mlh3-/- mice are infertile." (PMID 24639688, 2013). "To investigate this relationship, we studied the frequency of distribution of the common SNP C2531T in the MLH3 gene in 105 infertile patients and compared the results with 100 fertile controls in order to explore the possible association between gene variation and female infertility." (PMID 24639688, 2013). "Although it is not known whether the remaining genes may lead to female infertility, it is noteworthy that in seven of them (ADAD2, AR, C1orf146, MLH3, RAD21L1, SYCP3, and TERB1), the corresponding female KO mice are infertile." (PMID 40896145, 2025).
female infertility (4 papers, 2013 to 2025). Diminished or absent ability of a female to achieve conception. "Polymorphisms in human MLH3 genes have been associated with male and female infertility, and errors in meiotic chromosome segregation are considered a leading cause of spontaneous miscarriages and birth defects." (PMID 28827832, 2017). "The present study, evaluated, for the first time, the relationship of the C2531T polymorphism of the MLH3 gene with female infertility in a case-control study." (PMID 24639688, 2013). "Our results regarding analyzes of 105 patients and 100 controls, showed that the MLH3 C2531T polymorphism was associated with increased risk for the female infertility." (PMID 24639688, 2013). "In the present study, we found an association between the SNP C2531T (P844L) in the MLH3 gene and female unexplained infertility in blood samples, suggesting that this mutation may be an important genetic risk factor for female infertility in Iran." (PMID 24639688, 2013). "MLH3 protein plays a central role in meiotic recombination and it is reasonable to hypothesize that mutations in the MLH3 gene may be associated with male and female infertility." (PMID 24639688, 2013). "Inactivation of the MLH3 gene has been suggested to play a role in both male and female infertility." (PMID 29234393, 2017). "The further functional study will continue to provide new evidence of the role of the MLH3 in pathogenesis of female infertility and will help to further elucidate the mechanisms of meiotic recombination in mammal." (PMID 24639688, 2013).